EDN1 (endothelin 1)
Diseases named in the same sentence as EDN1 in open-access papers (continued):
Sharing a sentence is not in itself a finding about the gene and the disease.
endothelial dysfunction (continued). "As such, BA was found to reduce endothelial dysfunction by increasing the expression of endothelial nitric oxide synthase (eNOS), which further inhibited the expression of intracellular adhesion molecule-1 (ICAM-1) and endothelin-1 (ET-1) that promote the atherosclerotic plaque formation." (PMID 36012159, 2022). "The absence of any decrease in endothelin-1 level in plasma may indicate an insufficient effect of prednisolone on endothelial dysfunction." (PMID 36555286, 2022). "TsIIA plays a protective role by inhibiting strain-induced endothelin-1 (ET-1) expression, increasing the endothelin type B (ETB) receptors, reducing the ETA receptors, upregulating eNOS, and increasing the formation of NO during chronic intermittent hypoxia (CIH)-induced endothelial dysfunction." (PMID 31338034, 2019). "Endothelial dysfunction is indicated by decreased production of vasodilatory and homeostatic molecules such as nitric oxide (NO) and prostacyclin (prostaglandin I2, PGI2) or increased production of vasoconstrictive molecules such as endothelin-1 (ET-1) and thromboxane A2 (TXA2)." (PMID 26617606, 2015). "Endothelial dysfunction is characterized by impaired endothelium-dependent dilation (EDD) secondary to reduced bioactivity of the vasodilator molecule nitric oxide (NO), and increased vascular tone mediated by the potent vasoconstrictor peptide endothelin-1 (ET-1)." (PMID 25807234, 2015). "Transcript levels of hemeoxygenase 1 (HO-1), endothelin 1 (ET1), endothelin receptors A, B (ETA, ETB), tissue factor (TF), and plasminogen activator inhibitor-1 (PAI-1) were measured in the lung and heart to assess oxidative stress, endothelial dysfunction and coagulation cascade." (PMID 25442699, 2014). "Theoretically, increased endothelin-1 may link endothelial dysfunction to no-reflow; however, clinical studies could not establish this relationship in ST-segment elevation myocardial infarction (STEMI) patients managed by the primary percutaneous intervention (PCI)." (PMID 36178560, 2022). "Vasomotor endothelial dysfunction involving ADMA and endothelin-1 in the ICMP development has no distinctive features relative to CHD without cardiomyopathy." (PMID 37509589, 2023).
Hypertension (538 papers, 2004 to 2026). The presence of chronic increased pressure in the systemic arterial system. "Under pathological conditions, overexpression of EDN1 is associated with various cardiovascular diseases, such as hypertension and atherosclerosis." (PMID 40051702, 2025). "Endothelin-1 (ET-1) is a potent vasoconstrictor molecule released from endothelial cells, and its overproduction is associated with hypertension, atherosclerosis, and ischemic heart disease." (PMID 40277892, 2025). "Another single-nucleotide mutation, rs9349379, in the PHACTR1gene is associated with hypertension and increased Edn1 gene expression.Interestingly, the link with hypertension is inverse." (PMID 41524047, 2025). "The increase in vessel wall contractility caused by abnormal EDN1 expression contributes to increased peripheral resistance and thus plays a role in the pathogenesis of hypertension." (PMID 39456823, 2024). "Endothelin-1 (ET-1) is a vasoconstrictor molecule implicated in conditions such as hypertension, congestive heart failure, and inflammation." (PMID 38300319, 2024). "Increasing physical activity (PA) levels emerges as a promising avenue toaddress AF risk factors, such as obesity, hypertension, and diabetes mellitus,through mechanisms of reduced vasoconstriction, endothelin-1 modulation, andimproved insulin sensitivity." (PMID 39139428, 2024). "Endothelin‐1 (ET‐1) and its receptors are linked to increases in sensitivity of the chemoreceptors to hypoxic stress and the development of hypertension in preclinical models." (PMID 39218615, 2024). "Elevated levels of CRP can heighten the risk of hypertension by reducing the expression and activation of nitric oxide synthase, increasing endothelin-1 synthesis, and impairing endothelial-dependent vasodilation." (PMID 38515520, 2024). "Elevated levels of endothelin-1 (ET-1), a powerful vasoconstrictor, are linked to hypertension and increased vascular tone in PIH." (PMID 39105037, 2024). "A variety of vasoconstrictors (angiotensin II, endothelin 1, aldosterone, etc.)and vasodilators (nitric oxide, hydrogen sulfide, Nrf2, etc.)are strongly associated with the pathophysiologic pathways of hypertension and ED." (PMID 37025676, 2023). "The balance between vasoconstrictor and vasodilator mediators, such as nitric oxide (NO), prostacyclin (PGI2), and endothelin-1 (ET-1), regulates vascular tone, and a shift toward vasoconstriction is associated with hypertension progression." (PMID 36675310, 2023). "Nevertheless, the association with adverse cardiovascular outcome of endothelin-1 and somatostatin, related to hypertension and hormone regulation, respectively, was modified by sex in the current study." (PMID 37198662, 2023). "Body mass index was also higher in the hypertension group and presented significant associations with Endothelin 1 in the whole study population (p = 0.03)." (PMID 35626723, 2022). "Increased circulating endothelin-1, capillary rarefaction, and prostacyclin synthesis are also thought to be important mechanisms of hypertension associated with VEGF inhibition." (PMID 35566115, 2022). "In the view of location and ethnicity, we assume that it would be prudent to investigate the association between + 138 Ins/del A and + 5665 G/T polymorphisms in EDN1 gene and hypertension in Burmese people living in Magway Township, Myanmar." (PMID 35841119, 2022). "This study revealed that the + 138 Ins/del A polymorphism of the EDN1 gene is significantly associated with hypertension in Burmese living in Magway Township, Myanmar." (PMID 35841119, 2022). "The nitrogen oxide (NO)/endothelin-1 (ET-1) coefficient is a criterion for the risk of developing hypertension." (PMID 35222797, 2022). "The reduced serum NO bioavailability and upsurge in endothelin-1 have been positively linked with hypertension." (PMID 36434695, 2022). "Dyslipidemia is associated with elevated circulating levels of endothelin-1, causing the onset of hypertension." (PMID 35873005, 2022).
Hypertension (continued). "The purpose of this study was to investigate the associations between the + 138 insertion/deletion of adenine (Ins/del A) and + 5665 guanine-to-thymine (G/T) polymorphisms of the endothelin-1 gene and hypertension in the residents of Magway Township, Myanmar." (PMID 35841119, 2022). "Our data show that plasma levels of total Ubiquitin and Clusterin were similar in both groups, but reveal a positive significant association between Endothelin 1 and Ubiquitin in the plasma of individuals with hypertension." (PMID 35626723, 2022). "The other is systemic hypertension, which is caused by enhanced angiotensin II sensitivity accompanied by vasoconstriction through activation of endothelin-1." (PMID 34015042, 2021). "Endothelin-1 has been implicated in the development of hypertension, chronic heart failure, and acute MI." (PMID 33504164, 2021). "Another compound associated with renal fibrosis is endothelin-1 (ET-1), which is a potent vasoconstrictor that has been implicated in hypertension." (PMID 33668632, 2021). "Soluble endothelin-1 (ET-1) is increased in diabetes, hypertension, renal failure, and possibly linked to advanced atherosclerotic changes." (PMID 32337369, 2020). "Potential mechanisms implicated in VEGFi-induced hypertension include increased endothelin-1 (ET-1) levels, renin–angiotensin system activation, endothelial cell apoptosis, and microvascular rarefaction." (PMID 30753341, 2019). "Endothelin-1 (ET-1) contributes to regulation of vascular tone and has been implicated in the pathogenesis of different models of hypertension." (PMID 30606254, 2019). "Due to influential role of the endothelin pathway in hypertension development, we also investigated the association between EDN1 and EDNRA gene polymorphisms and ischemic stroke development in patients with and without AH." (PMID 29849817, 2018). "Gene-editing studies have established a genome-wide association studies (GWAS) SNP in chromosome 6p24, implicated in six conditions including hypertension, as a distal regulator of the endothelin-1 gene around 3000 base pairs away." (PMID 29881931, 2018). "While the pathogenesis of retinal vein occlusion (RVO) is still unclear, systemic hypertension and increased level of endothelin-1 (ET-1) are known risk factors." (PMID 30338274, 2018). "Loss of endothelial KLF4 is associated with increased hypertension and pulmonary artery vascularization, in part through enhanced expression of endothelin-1 (ET-1) and decreased eNOS expression." (PMID 29459900, 2018). "Several experiments have linked alcohol ingestion, high fat diet, and hypertension via a mechanism of elevated tissue angiotensin II levels, depletion of the endothelial nitric oxide generating system, and overproduction of endothelin-1." (PMID 25784949, 2015). "A number of previous studies have linked EDN1 rs1800541 and rs57072783 polymorphisms with hypertension in individuals with overweight and obesity, as well as with HDL cholesterol metabolism." (PMID 26594247, 2015). "The underlying mechanisms of hypertension in pregnancy in response to increased cytokine levels appear to involve activation of endothelin 1, increased oxidative stress, and activation of angiotensin II type 1 receptors." (PMID 26113950, 2015). "Endothelin-1, angiotensin II, and nitric oxide-cGMP pathway polymorphisms have also been linked to altered adrenergic vascular reactivity and are associated with hypertension." (PMID 25431686, 2014). "Systemic hypertension is a prominent feature in humans with metabolic syndrome (MS) and this is partly caused by an enhanced endothelin-1 (ET-1) mediated vasoconstriction." (PMID 22682151, 2012). "Endothelin-1 (ET-1) is a potent vasoconstrictor involved in the regulation of vascular tone and implicated in hypertension." (PMID 22096514, 2011).
Hypertension (continued). "Endothelin-1 is a potent vasoconstrictor that has been associated with both hypertension and arterial stiffness and further research into the impact of DE exposure on the endothelin system is anticipated." (PMID 19284640, 2009). "A possible explanation is that concurrent exercise may reduce plasma endothelin-1 concentration, a vasoconstrictor and risk factor for hypertension, thereby directly contributing to reductions in SBP." (PMID 41499584, 2026). "Hypertension may be caused by mechanisms including the activation of the renin-angiotensin system, oxidative stress, endothelial inflammation, endothelin-1 activation, and nitrous oxide reduction." (PMID 40000548, 2025). "The correlation between higher BMI and the risk of glucocorticoid-induced hypertension may be due to the increased levels of aldosterone and vasoconstrictor mediators, such as angiotensin II and endothelin-1, in obese patients." (PMID 40290310, 2025). "In addition, TNF-α can cause hypertension via stimulating the production of endothelin 1 and angiotensinogen." (PMID 38275420, 2024). "Increased endothelin-1 production were as a cause of hypertension in psoriasis." (PMID 38683749, 2024). "The sICAM and endothelin-1 are implicated in the activation or damage of cells such as platelets and endothelium and could be associated with high blood pressure." (PMID 38755622, 2024). "Physiologically, the hypothesis that hypertension causes ED is possible, because hypertension will lead to a continuous increase in the release of vasoconstrictors (e.g., Angiotensin receptor II, Endothelin-1 and aldosterone)." (PMID 37363097, 2023). "Amongst these polymorphisms, two variants of the EDN1 gene may play a role in the development of hypertension." (PMID 35841119, 2022). "However, significant positive associations between Endothelin 1 and protein aggregation or proteostasis biomarkers (such as fibrils and ubiquitin) were only observed in the hypertension group." (PMID 35626723, 2022). "The endothelin-1 pathway’s (ET-1) activation also causes hypertension." (PMID 34830100, 2021). "The association between obesity and hypertension may be explained by the increased plasma endothelin-1 and nitric oxide production and adiposity among obese individuals." (PMID 32138715, 2020). "Elevated circulating level of ET‐1 has been reported in aged humans and activation of endothelin‐1 system has been related to aging‐associated diseases, such as diabetes, atherosclerosis, hypertension, and cancer." (PMID 28857396, 2017). "Several genetic variants of EDN1, which may influence the hereditary risk of cardiovascular diseases such as coronary heart disease, hypertension, and ventricular arrhythmia have already been identified." (PMID 28197493, 2016). "Altered pulmonary vascular reactivity in hypertension may be related to a loss of endothelial buffering of vasoconstriction and decreased leptin-induced vasodilation in conditions of increased endothelin-1." (PMID 24499246, 2014). "Similar to studies on NOS gene SNPs, several studies suggest that some of the EDN1 SNPs may be associated with hypertension." (PMID 24063765, 2013). "Endothelin-1 (ET-1)-mediated activation of the endothelin-1 receptor is known to result in vasoconstriction and smooth muscle cell proliferation and is implicated in the pathogenesis of hypertension, coronary vasospasms, and heart failure." (PMID 21711548, 2011). "Given that endothelin-1 (ET-1), a potent vasoconstrictor, is implicated in the pathogenesis of hypertension, and that ET-1 has been shown to interact with calcium channels, we hypothesized that changes in blood ET-1 levels reflect the therapeutic efficacy of amlodipine." (PMID 40007810, 2025). "UA-mediated hypertension may also be caused by the up-regulation of thromboxane and endothelin-1." (PMID 33498870, 2021). "Moreover, it appears that endothelin-1 signaling may play a central role in the hypertension associated with preeclampsia." (PMID 22848831, 2012).
Hypertension (continued). "Mechanistically, the persistent contractile state of VSMCs is attributed to the increased levels of angiotensin II (AngII) and endothelin-1 (ET-1) as well as the over-activity of the sympathetic nervous system that accompany hypertension." (PMID 40867518, 2025). "Rac1 is activated in response to a myriad of hypertrophic stimuli, including but not limited to angiotensin II (AngII), phenylephrine (PE), endothelin-1 (ET-1), stretch, pressure overload and in multiple animal models of hypertension-induced heart disease." (PMID 41333012, 2025). "Dyslipidemia also contributes to higher level of endothelin-1 in circulation, which has mitogenic and vasoconstrictive properties, promoting the development of hypertension." (PMID 40664455, 2025). "Another proposed mechanism is that resistin increases the expression and release of endothelin-1 (ET-1) and downregulates endothelial nitric oxide synthase in human cells, resulting in hypertension." (PMID 40283140, 2025). "Pathological conditions (e.g., hypertension) induce endothelial endothelin-1 (ET-1) overexpression, which activates the cardiomyocyte CaMKII/NFATc3 pathway through ETA receptors, driving pathological hypertrophy." (PMID 40917801, 2025). "One of the most important pathologies in which endothelin-1 is involved is arterial hypertension, especially when resistant or difficult to control." (PMID 41153763, 2025). "∙ Inhibition of endothelin-1, a well-known strategy in the treatment of pulmonary hypertension, was recently approved to treat arterial hypertension." (PMID 41524047, 2025). "A common variation in a non‐coding gene sequence modulates the expression of EDN1 (the gene that encodes ET‐1) and has been associated with five prevalent vascular conditions: CAD, hypertension, migraine, carotid dissection, and fibromuscular dysplasia." (PMID 40692280, 2025). "One of the strongest endogenous vasoconstrictors, endothelin‐1 (ET‐1) is linked to a number of illnesses, including liver fibrosis, chronic kidney disease (CKD), hypertension, pulmonary hypertension, and atherosclerosis." (PMID 40692280, 2025). "According to studies, atorvastatin inhibits the IL-6/STAT3/endothelin-1 pathway in patients with spontaneous hypertension." (PMID 38855751, 2024). "It is somewhat unexpected that the rates of diabetes and hypertension were substantially lower in the other groups split according to the endothelin-1 cut-off." (PMID 39408883, 2024). "There is a growing body of evidence to indicate that endothelin-1 is involved in the pathogenesis of hypertension, cardiac hypertrophy and heart failure." (PMID 38786079, 2024). "Another pathophysiologic mechanism for hypertension involves theendothelin system, specifically endothelin-1 (ET-1), produced in the vascularendothelium." (PMID 38363454, 2024). "The involvement of endothelin-1 (ET-1) in the advancement of chronic kidney disease and the onset of hypertension is also fairly well understood." (PMID 39408883, 2024). "with hypertension, where training improves not only the levels of endothelin-1 but concomitantly also carotid artery compliance." (PMID 38571722, 2024). "Lifelong physical activity opposes an age-related increase in skeletal muscle and plasma levels of the potent vasoconstrictor endothelin-1, and 8 weeks of training normalizes plasma endothelin-1 levels in individuals with essential hypertension." (PMID 38571722, 2024). "PKCδ is also involved in promoting hypertension via endothelin-1 signaling, and inhibition of PKCε in hypertension-induced heart failure led to reduced pathological remodeling and improved myocardial function." (PMID 38139428, 2023). "During haemodialysis, patients with hypertension show an increase in endothelin-1 levels, while NO remains disproportionately low, leading to vasoconstriction." (PMID 37773103, 2023).